MET (MET proto-oncogene, receptor tyrosine kinase)
Diseases named in the same sentence as MET in open-access papers (continued):
Sharing a sentence is not in itself a finding about the gene and the disease.
tumor (continued). "Combining mTOR and c-MET inhibitors has demonstrated synergistic effects in reducing tumor growth in preclinical models, offering a new therapeutic strategy for this condition." (PMID 39329778, 2024). "More significantly, WntSI effectively overcame acquired resistance to EGFR‐TKIs resulting from MET amplification in both cell line‐derived and patient‐derived tumor xenograft mouse models, while demonstrating exceptional biosecurity." (PMID 38867713, 2024). "Both types of MET-CAR-T cells can overcome resistance to small molecule targeted drugs against MET, and their anti-tumor activity is correlated with MET expression levels." (PMID 38443969, 2024). "These alterations can result in abnormal activation of the MET signaling pathway, which, in turn, can drive tumor development and progression." (PMID 39751645, 2024). "Previously, this tumor was demonstrated to be sensitive to the MET inhibitor savolitinib alone or in combination with radiation." (PMID 38485737, 2024). "Assuming that the mutual interaction of tumor cells and TAMs determines the routes of MBM progression and fosters the activation of MET receptor-related processes, we investigated levels of MET signaling-associated genes." (PMID 38386085, 2024). "It was noted that c-MET inhibition augmented HTL recognition by decreasing TGF-β production by tumor cells." (PMID 39664377, 2024). "We then demonstrated that TWIST1 was required for tumor proliferation in MET altered NSCLC both in vitro and in vivo." (PMID 38485737, 2024). "The c-MET x CD137 BsAb was found to provide co-stimulation to T cells through cross-linking by c-MET-expressing tumor cells." (PMID 39664377, 2024). "In particular, while VEGFR inhibition alone can still allow tumour spread, due to the activation of the parallel hypoxia-induced MET signalling, this TKI can concurrently block both pathways, resulting in enhanced disease control." (PMID 37851242, 2024). "Treatment with capmatinib led to greatly reduced levels of phosphorylated MET, Erk and Akt in initial neoplasms of PD animals, whereas crizotinib treatment induced a less complete reduction compared to vehicle-treated mice." (PMID 38849845, 2024). "In spite of this, the involvement of the HGF/c-MET signaling axis in remodeling the tumor microenvironment (TME) remains relatively unexplored." (PMID 39201787, 2024). "In a xenograft nude mouse model, treatment with the one-armed anti-c-MET antibody significantly inhibited tumor growth in HepG2-bearing mice." (PMID 39664377, 2024). "These diabodies, which target both c-MET+ tumor cells and PD-1+ immune cells, demonstrate efficacy across cell lines expressing varying levels of c-MET." (PMID 39664377, 2024). "The treatment led to tumor shrinkage and manageable side effects, highlighting the potential of capmatinib in patients with specific genetic alterations like MET fusions." (PMID 39598385, 2024). "The human patient case study revealed a population of MET-amplified tumor cells that were resistant to EGFR-/BRAF-targeted therapy." (PMID 39626159, 2024). "Inhibiting c-MET resulted in heightened tumor growth and metastasis, underscoring the pivotal role of c-MET in neutrophil infiltration." (PMID 39664377, 2024). "For case 7, patient was found adenocarcinoma in the upper lobe of left lung and treated, then found another tumor in the upper lobe of right lung with MET exon 14 alteration and treated with crizotinib." (PMID 38902688, 2024). "The combination of NRP1-interfering molecules with MET-targeted drugs enhanced their effectiveness and prevented, or even reversed, the development of resistance in cancer cells and tumor models." (PMID 39769452, 2024). "By modulating immune responses and enhancing c-MET signaling pathways, Gal-7 promotes tumor growth and metastasis, indicating its critical role in the disease’s progression." (PMID 39664377, 2024).
tumor (continued). "Our data demonstrated that this combination significantly reduced tumor growth in this EGFR TKI resistant EGFR mutant MET amplified model." (PMID 38485737, 2024). "As a proof-of-concept study, we applied the identified procedures to the small-scale production of biparatopic anti-c-MET ADCs enabling cytotoxicity screens with tumor cells of varying c-MET expression levels." (PMID 38396776, 2024). "Further, we compared the effects of each pUMAP cluster on genes associated with critical HT29 tumor biomarkers: KRAS, BRAF, CDH1, CYNNB1, and MET." (PMID 39605490, 2024). "The patient's tumor developed resistance to BRAF/MEK/EGFR inhibition with MET amplification, but remained sensitive to FOLFIRI, suggesting MET amplification did not induce resistance to irinotecan." (PMID 39626159, 2024). "Despite the different mechanisms, MET alterations share a common role in promoting invasive growth, making tumor cells vulnerable to targeted therapies." (PMID 39598385, 2024). "By altering the composition and function of immune cells in the TME, HGF/c-MET signaling can inhibit the anti-tumor immune response, allowing tumor cells to evade immune system attacks." (PMID 39201787, 2024). "The c-MET inspired us to explore its function further since it was one of the top 2 genes in both the blue module and tumor driver genes (TDG)." (PMID 38352883, 2024). "Currently, several MET inhibitors, including small molecule tyrosine kinase inhibitors (TKIs) and monoclonal antibodies, have demonstrated promising anti-tumor activities in clinical trials." (PMID 39201787, 2024). "We observed that MET is primarily expressed in tumor cells and to a lesser extent in immune (T cells) cells/NK cells, macrophages, CAF or endothelial cells." (PMID 38386085, 2024). "c-MET inhibitors, such as crizotinib, cabozantinib, and tivantinib, have shown promise in inhibiting tumor growth and metastasis but can be limited by compensatory mechanisms and immunosuppressive TME." (PMID 39664377, 2024). "This mode of action has lately been exploited for both enhanced degradation of oncogenic c-MET for anti-tumor treatment as well as enhanced payload delivery of highly potent ADC approaches." (PMID 38396776, 2024). "While crizotinib caused tumor regression in c-MET-amplified xenografts, the effect on [18F] FDG uptake differed between tumor types." (PMID 38892979, 2024). "Since hepatocyte growth factor (HGF) is the sole ligand for MET and is enriched in the tumor microenvironment, we first evaluated the function of MET on phosphorylating and activating STAT5A with the treatment of HGF in both LNCaP and C42B cells." (PMID 38745318, 2024). "Next, analysis of focus formation, cell motility, and tumour growth in athymic mice demonstrated a correlation between MET enzymatic activity and the transforming properties of the different mutants." (PMID 38652103, 2024). "Combining c-MET inhibitors with PD-1/PD-L1 inhibitors is being evaluated for its potential to enhance the anti-tumor immune response." (PMID 39664377, 2024). "Despite the mixed results of c-MET inhibition, with some studies demonstrating enhanced tumor growth and metastasis while others suggest improved immunotherapy efficacy, its potential cannot be overlooked." (PMID 39664377, 2024). "These tumor formations have been effectively suppressed using Met inhibitors, supporting the advancement of the use of a MET inhibitor in the clinic." (PMID 38334610, 2024). "Conversely, dampening c-MET activity has been shown to stabilize PD-L1, enabling tumor cells to evade T cell responses, thereby contributing to the limited success of c-MET inhibitors in clinical trials targeting non-small cell lung cancer (NSCLC)." (PMID 39664377, 2024). "Some authors bypassed the evaluation of every MET-CAR construct specificity/selectivity by proposing MET-CAR-T delivery exclusively at the tumor site." (PMID 38892318, 2024).
tumor (continued). "Accordingly, we conducted a metabolome-wide profiling of a panel of MET-driven cancer cells and tumor xenografts in their unperturbed state and upon METi." (PMID 38957115, 2024). "In fact, targeting MET alongside VEGF inhibition can reduce tumor aggressiveness in preclinical pancreatic and neuroblastoma cancers." (PMID 39598385, 2024). "In contrast, c-MET activation recruits Tregs and induces the expression of immune checkpoint molecules, such as PD-L1, on tumor cells." (PMID 39664377, 2024). "This therapy, specifically targeting MET, has shown promising results in enhancing the anti-tumor activity of CAR-T cells and overcoming immunosuppression in solid tumor microenvironments." (PMID 39201787, 2024). "Other key driver gene amplifications, specifically MET, EGFR and FGFR2, in circulating tumor DNA were associated with numerically lower ORR." (PMID 38745009, 2024). "Interactions between CAFs and cancer cells activate the HGF/MET signaling pathway, leading to tumor growth and metastasis." (PMID 37887325, 2023). "Patients were included beyond progression in second-line chemotherapy and screened for MET protein expression by immunohistochemistry (IHC) to be 2+ or 3+ positive in more than 60% of tumor cells." (PMID 37046637, 2023). "We established HER3‐and/or MET‐KO SW1116 cell lines, and HER3/MET‐double KO resulted in the inhibition of in vitro cell proliferation and in vivo tumor growth in nude mice by SW1116 cells." (PMID 36751113, 2023). "MET, a receptor protein mainly found in epithelial cells, plays a crucial role in embryogenesis, tumor growth, and metastasis." (PMID 38077251, 2023). "It is well known that cytokines secreted by CAFs play a significant role in tumor growth; among these cytokines, HGF is secreted mainly by CAFs and acts on MET-positive cancer cells in the tumor microenvironment." (PMID 37887325, 2023). "c-MET is a prognostic factor of OC patients, targeting c-MET inhibits peritoneal dissemination, tumor invasion, and metastasis in vivo." (PMID 36959862, 2023). "Mutations in the MET gene lead to abnormal expression of the MET axis, promoting the migration and invasion of tumor cells, as well as resistance to inhibitors targeting EGFR and VEGFR." (PMID 37444584, 2023). "In both in vitro and in vivo models, the HNC018 showed anti-tumor properties via downregulating the c-MET/STAT3/AKT signaling axis in HNSCC." (PMID 37373393, 2023). "Mostly, staining intensities are classified as negative, weak (1+), moderate (2+), and strong (3+), and a staining intensity of 2+ in at least 50% of tumor cells is classified as MET overexpression." (PMID 37296895, 2023). "Together with its ligand, hepatocyte growth factor (HGF), MET plays an important role in tumor proliferation, angiogenesis, and migration." (PMID 37296895, 2023). "Based on the pathologic assessment, c-MET IHC staining was analyzed and quantified in tumor, mucosal epithelium, and deep margin (i.e., healthy muscle tissue)." (PMID 36184713, 2023). "Studies have demonstrated that many tumor patients have c-MET overexpression and gene amplification during the incidence and metastasis of their malignancies." (PMID 36979146, 2023). "Merestinib was originally developed to target MET and is an oral kinase inhibitor with antitumor, antiangiogenic, and antiproliferative activity in tumor models." (PMID 37901797, 2023). "BPI-9016 M is a c-MET inhibitor that inhibits tumor growth by promoting tumor cell apoptosis and facilitating DNA damage." (PMID 36646686, 2023).
tumor (continued). "Contrary to expectations, MET‐KO promoted in vitro cell proliferation and in vivo tumor growth of SW1116." (PMID 36751113, 2023). "The broad range of critical biological responses induced by MET awards this oncogene as a crucial oncogene in tumor progression, enabling cancer cells to survive and escape the hostile primary tumor microenvironment and form distal metastases." (PMID 37760640, 2023). "The HGF/c-MET pathway has been found to be aberrantly activated in a variety of tumors and plays a key role in various biological processes such as tumor occurrence, proliferation, metastasis, angiogenesis, and stemness." (PMID 37919751, 2023). "Intriguingly, we discovered that the expressions of MET, STAT3, and AKT were linked with the tumor stage using the web-based application GEPIA." (PMID 37373393, 2023). "The role of HGF and its TK receptor MET in tumor growth, metastasis development, and therapeutic resistance is well-established." (PMID 37298116, 2023). "Multiple studies demonstrated its remarkable potential; DN30 hampers cell growth and induces apoptosis in multiple MET-addicted cell lines in vitro, and induces an impressive reduction of tumor mass in vivo." (PMID 37760640, 2023). "Capmatinib (Tabrecta), tepotinib (Tepmetko), (Cabometyx), cabozantinib, glesatinib, and merestinib are MET inhibitors that directly target the MET protein and reduce the growth of tumor cells in NSCLC." (PMID 37901797, 2023). "The administration of SCC244 has shown strong anticancer efficacy at well‐tolerated levels in xenografts of human tumor cell lines or NSCLC and HCC patient‐derived tumor tissue driven by MET abnormality." (PMID 38077251, 2023). "Very recently published preclinical data suggest augmented antitumoral activity using in vivo models of the dual targeting of EGFR and MET in this particular tumor type." (PMID 37370859, 2023). "In summary, this comparative transcriptome analysis of matched melanoma tumor biopsies before and during progression highlights increased expression of c-MET and YAP as drivers of acquired resistance." (PMID 37174072, 2023). "Clinically, circulating-tumor cells (CTCs), which express EpCAM, MET, and CD44, identify a subset with increased metastasis-initiating phenotype, suggesting that CD44v6 plays an important role in cancer-initiating cell property cooperating with MET." (PMID 36835416, 2023). "ABT-700, a humanized antibody, has completed phase I clinical trials for several solid tumors and has demonstrated tumor regression in preclinical cancer models with MET amplification." (PMID 37692610, 2023). "Unexpectedly, the tumor shows TFCP2 rearrangement with coexistence of increased copy numbers of EWSR1 and ROS1 gene and MET gene mutation." (PMID 36998041, 2023). "The currently available data defining the biological role of MET as a master driver of the invasive growth program strongly indicates that this receptor can be crucial during tumor progression, favoring the malignant phenotype." (PMID 37345079, 2023). "In turn, activated CAFs can stimulate the HGF/c-MET axis in tumor cells through the secretion of HGF, further enhancing tumor stemness, invasion, and metastasis." (PMID 37919751, 2023). "Accordingly, both in vitro models of MET-driven acquired resistance and analysis of primary tumor specimens supported the ability of circMET to discriminate tumor cells and patient samples characterized by high MET expression and phosphorylation." (PMID 37170152, 2023). "The HGF/c-MET axis and Hh pathway play critical roles in the interaction between tumor cells and CAFs." (PMID 37919751, 2023).
tumor (continued). "This review aims to provide an overview of the current understanding of the HGF/c-MET axis and Hh pathway in tumor cells and CAFs, as well as their interaction with each other." (PMID 37919751, 2023). "Compared to other cell subtypes in the tumour microenvironment, the expression of MET, MUC16, and KRT7 was higher in pancreatic malignant cells." (PMID 37815881, 2023). "In contrast, circMET showed a strong positive correlation with MET levels in both tumor cell lines and primary specimens, suggesting its potential application for tracking the status of the MET gene." (PMID 37170152, 2023). "In cancer, the MET proto-oncogene is abnormally activated and stimulates other signaling pathways in tumor cells, notably PI3K/AKT, JAK/STAT, Ras/MAPK, SRC, and Wnt/beta-catenin." (PMID 37509224, 2023). "The hepatocyte growth factor/c-MET signaling pathway aids tumor formation by promoting cell proliferation, survival, and motility." (PMID 37547755, 2023). "The loss-of-function mutations in this tumor-suppressor gene result in the accumulation of HIF1α/2α, eventually leading to overexpression of VEGF/PDGF, AXL, and MET, among others." (PMID 37400554, 2023). "The MET signaling pathway is also involved in the motility of tumor cells and is particularly important for acquiring an invasive property via RhoA and Src." (PMID 37547755, 2023). "In this study, we showed that HGF, which can be produced by fibroblasts in the tumor microenvironment, induces entrectinib resistance by activating its receptor MET and downstream signaling pathways in NTRK1‐rearranged or ROS1‐rearranged tumor cells." (PMID 36416133, 2023). "It is noteworthy that many stimuli that trigger MET transcription in cancer cells also lead to HGF upregulation in the tumor stroma, creating a feedforward stimulatory circuit that enhances MET activation." (PMID 38077251, 2023). "Herein, we provide in vitro and in vivo evidence that HNC018 exhibits anti-tumor effects by suppressing the c-MET/STAT3/AKT signaling axis." (PMID 37373393, 2023). "Pemigatinib treatment also caused the upregulation of microRNAs (miR-133b, miR-139, miR-186, miR-195) with tumor suppressor functions, along with the downregulation of validated protein targets with oncogenic roles (c-Myc, c-MET, CDK6, EGFR)." (PMID 37715207, 2023). "Yet, MET alterations have been found in both circulating-free DNA (cfDNA) and circulating tumor cells (CTCs) both at diagnosis and at resistance to EGFR TKIs." (PMID 37509224, 2023). "VEGFR and MET are known to promote tumor growth and metastasis by regulating angiogenesis, cell proliferation, cell migration, and epithelial-to-mesenchymal transition." (PMID 38264122, 2023). "The first test for scoring MET overexpression is performed by analysis of the percentage of positive tumor cells (scale 0–100%) with a staining intensity of 0 to 3+: negative, weak (1+), moderate (2+) or strong (3+)." (PMID 37046637, 2023). "The mesenchymal–epithelial transition (MET) gene is an oncogene that encodes RTK, which binds to the hepatocyte growth factor (HGF) and promotes the aggressive nature of the tumours by inducing angiogenesis." (PMID 37760531, 2023). "Subsequent research also demonstrated the continued effectiveness of glesatinib in METex14 and type I MET inhibitor-resistant tumor models and patients." (PMID 37919751, 2023). "Periodic calculation of growing tumor volumes revealed that tumor growth was strongly inhibited in HER3/MET‐dKO SW1116 tumors, as compared to parental SW1116 tumors." (PMID 36751113, 2023). "In xenograft models, cMet inhibitors (anti-HGF, anti-MET, and MET-targeted small molecule inhibitors) decrease tumour progression and the expression of stem markers such as CD133, Sox2, and Nanog." (PMID 37368660, 2023). "For example, MET inhibitors suppress liver tumor development in nude mice yet lose tumor suppressive activity in immunocompetent mice due to upregulation of PD-L1 expression." (PMID 37416781, 2023).